CFAP90 (cilia and flagella associated protein 90)
Description:
Microtubule inner protein (MIP) part of the dynein-decorated doublet microtubules (DMTs) in cilia axoneme, which is required for motile cilia beating.
Synonyms: C5orf49; LOC134121
Tractability: Small molecule: a structure with a bound ligand is known.
Gene: Protein-coding gene on chromosome 5 (7,830,378 to 7,851,512, reverse strand). Ensembl gene ENSG00000215217.
Subcellular location: Cytoplasm, cytoskeleton, cilium axoneme; Cytoplasm, cytoskeleton, flagellum axoneme
Gene Ontology:
Molecular function: protein binding
Biological process: flagellated sperm motility
Cellular component: axoneme; ciliary basal body; axonemal B tubule inner sheath; sperm flagellum
Genetic constraint (gnomAD): Loss-of-function variants: 7 observed, 5.89 expected, observed/expected ratio (o/e) 1.19, 90% interval 0.66 to 1.86. That is too few expected variants to judge how well the gene tolerates losing a copy. Missense variants: 155 observed, 125.31 expected, observed/expected ratio (o/e) 1.24, 90% interval 1.09 to 1.41. Synonymous variants: 69 observed, 53.88 expected, observed/expected ratio (o/e) 1.28, 90% interval 1.05 to 1.57.
Homologues: Orthologues: chimpanzee CFAP90 (99% identical), macaque CFAP90 (95% identical), guinea pig CFAP90 (82% identical), dog CFAP90 (80% identical), pig CFAP90 (79% identical), rabbit CFAP90 (79% identical), mouse Cfap90 (73% identical), rat Cfap90 (61% identical), zebrafish cfap90 (39% identical).